TLR4 (toll like receptor 4)
Diseases named in the same sentence as TLR4 in open-access papers (continued):
Sharing a sentence is not in itself a finding about the gene and the disease.
Thrombocytopenia (38 papers, 2009 to 2026). A reduction in the number of circulating thrombocytes. "A study by Chiao‐Hsuan Chao and group demonstrated that NS1 directly activates platelets via TLR4, promoting aggregation, adhesion to endothelial cells, and macrophage‐mediated phagocytosis of platelets, thereby causing thrombocytopenia." (PMID 41584400, 2026). "Recently, a report demonstrated the knockout TLR4 can inhibit thrombocytopenia and hemorrhage caused by Dengue virus in mice." (PMID 35796625, 2022). "Plasma leakage has also been associated with the interaction between the NS1 viral protein and toll-like receptor 4, which, in turn, also causes the activation of platelets, leading to thrombocytopenia through an enhancement of platelet aggregation." (PMID 34696384, 2021). "Platelet TLR4 mediates microvascular thrombosis and thrombocytopenia in response to LPS, thereby fostering tissue injury caused by vessel occlusion." (PMID 31379873, 2019). "Two previous studies using genetically modified mice have demonstrated that TLR-4 deficiency attenuates lipopolysaccharide induced thrombocytopenia." (PMID 29734352, 2018). "In the case of classical NEC, excessive lipopolysaccharide-induced TLR4 signaling likely contributes to thrombocytopenia and bone marrow suppression." (PMID 40201118, 2025). "The second mechanism is associated with platelet activation via the TLR4-MyD88-cGMP-protein kinase G (PKG) pathway, which exacerbated platelet aggregation and caused thrombocytopenia in response to injection of LPS." (PMID 41210196, 2025). "For instance, the potential synergistic effects of combining rhTPO with IVIG or TLR4 antagonists in septic patients with thrombocytopenia should be explored in preclinical and clinical studies." (PMID 40003683, 2025). "A recent study also reported that DENV NS-1 activates platelets via TLR4, which leads to thrombocytopenia and hemorrhage." (PMID 36251659, 2022). "For patients with dengue, TLR4 on platelets binding with DENV NS1 is triggered, causing thrombocytopenia and hemorrhage." (PMID 34394108, 2021). "TLR4 is also highly expressed in platelets, and when bacterial lipopolysaccharide (LPS) binds to TLR4, it can result in thrombocytopenia and the accumulation of platelets in the lungs." (PMID 34835282, 2021). "It has been observed that septic patients with thrombocytopenia had higher levels of TLR4 expressed on the platelet surface and more sCD40L in circulation, indicating increased activation levels." (PMID 33092021, 2020). "As bacterial LPS can induce rapid thrombocytopenia, the literature suggests that activation of platelets through TLR4 can be a major mechanism for such thrombocytopenia in sepsis." (PMID 33092021, 2020). "It was quickly followed by another study with similar results showing that functional TLR4 is required for LPS-induced thrombocytopenia." (PMID 33092021, 2020). "We also proved that both NS1 and TLR4 are critical for DENV-induced thrombocytopenia and hemorrhage using a DENV-induced hemorrhagic mouse model." (PMID 31009511, 2019). "This suggests that even if IVIg can modulate TLR4 signaling, it cannot inhibit LPS mediated thrombocytopenia under the conditions studied." (PMID 23940791, 2013). "Dengue NS1 protein induces thrombocytopenia via TLR4 activation and platelet aggregation." (PMID 40007026, 2025). "Intraperitoneal lipopolysaccharide (LPS) injection in wild-type mice reduces platelet counts by approximately 60% and this effect is absent in TLR4-deficient mice, confirming the role of TLR4-mediated necroptosis in LPS-induced thrombocytopenia." (PMID 40710328, 2025). "Furthermore, LPS-induced thrombocytopenia is reduced because the expression of TLR4 is significantly decreased in activated platelets." (PMID 37841241, 2023). "NS1 binds to platelets TLR4 and that triggers platelet aggregation and enhances platelet adhesion to endothelial cells and phagocytosis by macrophages, which may contribute to thrombocytopenia and hemorrhage during DENV." (PMID 36016430, 2022).
Thrombocytopenia (continued). "This clearly highlights the role of TLR4 in the process of LPS-induced thrombocytopenia." (PMID 35884941, 2022). "In neonates, thrombocytopenia driven by LPS in Gram-negative sepsis is thought to be related to diminished expression of platelet Toll-like receptor 4 (TLR4) and is linked to elevated mortality rates." (PMID 35204352, 2022). "Finally, we demonstrated that DENV-induced thrombocytopenia and hemorrhage were attenuated in TLR4 knockout and wild-type mice when NS1 was depleted from DENV supernatant." (PMID 31009511, 2019). "Since both NS1 and LPS can activate cells through TLR4, in this study, we propose and test the hypothesis that NS1 can induce platelet activation and enhance aggregation through TLR4, leading to thrombocytopenia and hemorrhage during dengue infection." (PMID 31009511, 2019). "We found that DENV NS1 could directly activate platelets through TLR4 and could further enhance platelet aggregation, adhesion to endothelial cells and phagocytosis by macrophages, which could lead to thrombocytopenia." (PMID 31009511, 2019). "Taken together, these results suggest that the binding of DENV NS1 to TLR4 on platelets can trigger its activation, which may contribute to thrombocytopenia and hemorrhage during dengue infection." (PMID 31009511, 2019). "Although platelets express functional TLR4 mediating neutrophil-dependent pulmonary sequestration, whether calpain contributes to thrombocytopenia in response to LPS is still unknown." (PMID 24489676, 2014). "Additionally, Andonegui G. demonstrated that platelets express TLR4, which contributes to thrombocytopenia." (PMID 24489676, 2014). "The observation that anti-platelet antibody resulted in thrombocytopenia in Myd88 deficient mice suggests that, similar to TLR4, Myd88 expression is not required for the induction of thrombocytopenia in the murine ITP model." (PMID 23940791, 2013). "LPS can also induce thrombocytopenia, potentially through LPS interaction with the TLR4/Myd88 signaling pathway, and platelet aggregation may play a role in this process." (PMID 23940791, 2013). "O157LPS injected intraperitoneally into mice leads to TLR4-mediated thrombocytopenia." (PMID 19750223, 2009). "Indeed, thrombocytopenia was observed after administration of LPS only in wild-type mice, not in TLR4-deficient mice." (PMID 35884941, 2022). "Furthermore, lipopolysaccharide (LPS), the major TLR4 ligand, induced thrombocytopenia in wildtype but not in TLR4-deficient mice." (PMID 35741086, 2022). "In conclusion, this study preliminarily demonstrates that elevated extracelluar HMGB1 induced high levels of ROS via both TLR4 and RAGE receptors of platelets, which in turn participates NLRP3 inflammasome activation leading to thrombocytopenia in HS rats." (PMID 35945940, 2022). "During inflammation, IL-8 levels, along with high expression levels of toll-like receptor 4 (TLR4) on macrophages and platelets, are reported to contribute to thrombocytopenia through neutrophil-dependent pulmonary sequestration." (PMID 33721196, 2021). "Taken together, these results suggest that viral NS1 and host TLR4 proteins are critical for DENV-induced hemorrhage and thrombocytopenia during DENV infection." (PMID 31009511, 2019). "TLR4 is involved in rapid TNF-α induction, NET formation, and thrombocytopenia." (PMID 31379873, 2019). "Administration of anti-platelet antibody to either C3H/HeJ mice or control C3H/HeNCrl mice resulted in the same degree of thrombocytopenia in both strains, suggesting that antibody induced thrombocytopenia does not rely on functional TLR4." (PMID 23940791, 2013). "Here, we demonstrate that the TLR4 agonist LPS does not inhibit IVIg or KM114 amelioration of antibody-induced thrombocytopenia, and that these therapeutics do not ameliorate LPS-induced thrombocytopenia." (PMID 23940791, 2013).
Thrombocytopenia (continued). "LPS administration did not inhibit the ability of IVIg or KM114 to ameliorate antibody induced thrombocytopenia, suggesting that putative ligation of TLR4 with LPS does not affect the therapeutic properties of IVIg or KM114." (PMID 23940791, 2013). "Injection of C3H/HeJ mice or control C3H/HeNCrl mice (express functional TLR4) with anti-platelet antibody resulted in severe thrombocytopenia (columns 2 vs 5) with no discernable difference in platelet counts between the 2 groups." (PMID 23940791, 2013). "As expected, we found that high-titer DENV could induce prolonged bleeding time, hemorrhage and thrombocytopenia in C57BL/6J wild-type mice but not in TLR4-/- mice." (PMID 31009511, 2019).
fungal infection (37 papers, 2009 to 2026). "On the other hand, TLR4 has a scientific framework directly related to fungal infections, such as candidiasis and paracoccidioidomycosis, caused, respectively, by the fungi Candida albicans and Paracoccidioides brasiliensis." (PMID 36506333, 2022). "In this sense, it has been reported that the interaction between P. brasiliensis and TLR4 lead to a severe fungal infection, associated with an enhanced exacerbated proinflammatory response." (PMID 29040281, 2017). "According to previous literature, the recognition of P. brasiliensis yeasts by PMNs involves different cell surface receptors, including dectin-1, mannose receptor (MR), and TLR2 or TLR4, which act collaboratively to provide mechanisms of resistance or susceptibility to fungal infection." (PMID 31886295, 2019). "Using another experimental model, it was seen that in comparison with TLR4−/-, TLR4-sufficient mice presented reduced proliferation of Treg cells, an augmented influx of activated T lymphocytes and macrophages to the lungs and a more severe fungal infection than TLR4-deficient mice." (PMID 30067137, 2019). "A similar disease outcome was observed in another study conducted by our group, in which TLR4-sufficient mice displayed impaired expansion of Treg cells, augmented influx of activated T lymphocytes and macrophages to the lungs and consequent more severe fungal infection than TLR4-deficient mice." (PMID 26512987, 2015). "In addition to TLR2, other TLRs, such as TLR4, have been implicated in the innate recognition of fungal infection." (PMID 26091522, 2015). "The expression of mRNAs for Interleukin-1β (IL-1β), TNFα, and TLR4 were evaluated in the corneas of the mice with fungal infection and the control corneas by real-time PCR." (PMID 31285488, 2019). "Our network pharmacology analysis predicted that XBJ regulates type I interferon and its upstream regulators such as interferon α, TLR2, and TLR4 in invasive fungal infection." (PMID 31969817, 2019). "A year after the discovery of the role of drosophila Toll protein in the host defense against fungal infection, a mammalian homologue was identified, referred to as TLR4." (PMID 22577589, 2012). "While another group found that TLR4 signaling impaired the expansion of Tregs during a fungal infection." (PMID 21695198, 2011). "We and others have previously shown that hypha formation is crucial for C. albicans pathogenicity and induction of proinflammatory responses at mucosal surfaces, which results in PMN-dependent TLR4-mediated protection against subsequent fungal infection." (PMID 20833374, 2010). "One proposed mechanism is that variations in the TLR4 gene alter cytokine production, which may affect the inflammatory response and the clearance of fungal infections." (PMID 41295183, 2025). "Furthermore, despite the common mechanism of NF-κB transcriptional regulation for miR-146 and miR-155, they differently control the TLR4 signaling pathways, which plays important role in phagocytes for fungi infection recognition." (PMID 35909603, 2022). "In this work, the authors suggest that other receptors like TLR-2 and Dectin-1 may also contribute to the immune response during S. schenckii infection, but they assign TLR-4 an important role in governing the functions of macrophages in fungal infection." (PMID 34358055, 2021). "In addition, the mRNA expression of IL-1β, TNFα and TLR4 was significantly increased in the corneas with fungal infection, compared with the control group in which only DMSO injection was administrated (P < 0.05)." (PMID 31285488, 2019). "However, there are few studies on the effects of TLR2 and TLR4 activation during the course of this fungal infection." (PMID 27458431, 2016). "TLR2 and TLR4 are known to be involved in the host innate immune response to fungal infection." (PMID 26039076, 2015).
fungal infection (continued). "To the best of our knowledge, we present the first study evaluating the role of TLR4 signaling and IDO-1 production by MDSCs in fungal infection, notwithstanding intriguing outcomes documented in other cell populations." (PMID 37524886, 2023). "A study suggested that TLR4 is an upregulated representative target in keratitis of bacterial infection, whereas SOD2 is an upregulated representative target in keratitis of fungal infection from Differentially Expressed Genes (DEGs)." (PMID 35216171, 2022). "The accumulated evidence implicates that TLR4 and TNFα are important in the pathogenesis of fungal infection, hence, we investigated if SAHA affects fungal keratitis due to the inhibition of key cytokines-TNFα and the inactivation of TLR4." (PMID 31285488, 2019). "PCN was shown herein to be efficient also as a therapy against the ongoing mycosis, and the observed Th1 immunity was attributed to PCN interaction with N-glycans of TLR2 and TLR4." (PMID 25474158, 2014). "Toll-like receptors (TLR2, TLR4), pro-inflammatory cytokines [tumor necrosis factor, interleukin 6 (IL-6), IL-1, and interferons], nuclear factor κB signaling, and HMGB1 were among top upstream regulators of the targets in fungal infection." (PMID 31969817, 2019). "MyD88 is also essential for TLR2 and TLR4 signaling, yet the role of TLR2 and TLR4 is not clear in the development of corneal opacification; TLR4−/− mice have an impaired ability to clear the infection so TLR4−/− is important in eradicating fungal infection." (PMID 28324534, 2015). "Moreover, we observed that expression of TLR2 and TLR4 was significantly higher in patients with AML and bacterial infection in comparison with group with separate fungal infection (ΔCt TLR2 1.15 ± 1.06 vs 0.66 ± 0.51 and ΔCt TLR4 0.45 ± 0.38 vs 0.21 ± 0.19)." (PMID 25412934, 2014). "Moreover, we observed that expression of TLR2 and TLR4 was significantly higher in patients with AML and bacterial infection in comparison with the group with isolated fungal infection." (PMID 25412934, 2014). "Because the LPS stimulus (TLR4 agonist) induces IL-10 production that is not controlled by galectin-3, we suppose that our observations may be peculiar to fungal infections." (PMID 19229338, 2009). "However, fungal infection is commonly recognized via the TLR2, TLR4 and TLR6 signaling pathways and does not result from the secretion of IFN-I." (PMID 24660033, 2014).
leptospirosis (37 papers, 2012 to 2025). A contagious bacterial infection caused by spirochetes of the genus Leptospira. "Some studies showed that delayed immune response was associated with severe leptospirosis, and TLR4 was very important in the control of leptospirosis." (PMID 33232366, 2020). "In this study, we aimed to explore the effect of the classical activator (LPS) of TLR4 on leptospirosis in susceptible and resistant hosts." (PMID 33232366, 2020). "C3H/HeJ mice are TLR4 gene deficient, but more susceptible to L. interrogans and display typical histopathological changes of leptospirosis compared to other species of mice." (PMID 28700741, 2017). "Our data suggest a protective role of TLR4 in strain 56606v clearance, while the receptor is also associated with bleeding in acute leptospirosis, possibly through induction of downstream proinflammatory mediators." (PMID 28536433, 2017). "In an effort to investigate the effect of TLR variants, especially TLR2 and TLR4, we genotyped the most studied variants in a high risk population exposed to leptospirosis." (PMID 25255143, 2014). "Although the C57BL/6 strain resists infection with pathogenic Leptospira species, mice with TLR2 and TLR4 double knock-out serve as a model of acute lethal leptospirosis." (PMID 22870312, 2012). "Overall, we hypothesize that these innate immune mechanisms could play a role in determining host susceptibility to leptospirosis and suggest a central, yet complex, role for TLR4." (PMID 35937697, 2022). "It is therefore proposed that TLR4 is essential to the resistance of the murine model, but the lack of recognition by human TLR4 is not the main reason for the enhanced human susceptibility to leptospirosis." (PMID 35937697, 2022). "Because human TLR4 does not sense the atypical leptospiral-LPS, we hypothesized that TLR4/MD-2 humanized transgenic mice (huTLR4) may be more susceptible to leptospirosis than wild-type mice, and thus may constitute a model of acute human leptospirosis." (PMID 33519799, 2020). "Furthermore, we and others developed mouse models of lethal and sublethal leptospirosis using C3H-HeJ mice that have a point mutation in the cytoplasmic domain of the tlr4 gene." (PMID 33519799, 2020). "Indeed, after a 6-week regimen of intermittent oral gavage, it was shown that treatment with the parental L. plantarum strain protected mice from acute leptospirosis in the sensitive C3H/HeJ TLR4-deficient model." (PMID 33123147, 2020). "Moreover, TLR4-deficient mice develop clinical signs of severe leptospirosis, which show that murine TLR4 protect mice from developing leptospirosis." (PMID 29974037, 2018). "Consequently, mice deficient for TLR4 (TLR4KO) are sensitive to leptospirosis, while parental wild type (WT) mice are resistant to the infection." (PMID 29211798, 2017). "However, we and others have shown that mice, immunosuppressed or genetically deficient for TLR4 or B cells, proved to be more sensitive, and develop lethal acute leptospirosis, demonstrating the usefulness of these murine models to unravel key components of the innate defense against leptospirosis." (PMID 25474719, 2014). "The goal of this study was to determine if the TLR4 competent strains can also be used as mouse models of sublethal leptospirosis." (PMID 40445994, 2025). "The data shows that although tlr4 does affect the virulence of leptospirosis (only C3H-HeJ succumbed to infection), the tlr4 competent strains (C3H-HeN and C57BL/6) also developed measurable sublethal leptospirosis." (PMID 39975062, 2025). "Since TLR2 and TLR4 play important roles in protection against leptospirosis and this differential recognition was attributed to co-purified lipoprotein, it was of interest to test the innate activity of our highly pure LPS in different host macrophages." (PMID 37935355, 2023). "In contrast, TLR4 activation is described in mice, a leptospirosis resistant species, but less clear in human cells." (PMID 35386703, 2022).